RNU6-954P (RNA, U6 small nuclear 954, pseudogene)
Gene: Small nuclear RNA gene on chromosome 21 (13,968,489 to 13,968,595, reverse strand). Ensembl gene ENSG00000223287.
Homologues: Orthologues: chimpanzee U6 (100% identical), macaque U6 (94% identical), dog U6 (71% identical), mouse Gm54642 (59% identical), mouse Gm22279 (58% identical), rat LOC120101210 (57% identical). Paralogues in human: RNU6-55P (99% identical), RNU6-316P (97% identical), RNU6-1193P (94% identical), RNU6-1269P (94% identical), RNU6-368P (94% identical), RNU6-538P (94% identical), RNU6-1320P (93% identical), RNU6-599P (93% identical), U6 (93% identical), U6 (92% identical), RNU6-821P (89% identical), RNU6-798P (87% identical), and 1290 more.